RSF1 (remodeling and spacing factor 1)
Diseases named in the same sentence as RSF1 in open-access papers (continued):
Sharing a sentence is not in itself a finding about the gene and the disease.
serous carcinomas (2 papers, 2012). "In high-grade serous carcinomas, a significant correlation (P < 0.0001) in expression level (both in intensity and percentage) was found between pChk2 and Rsf-1 (HBXAP), a gene involved in chromatin remodeling that is amplified in high-grade serous carcinoma." (PMID 22028712, 2012). "Rsf-1 immunostaining results were available in 75 primary high-grade serous carcinomas from our previous study, enabling correlation with pChk2 data." (PMID 22028712, 2012). "The Rsf-1 gene, located at ch11q13.5, is frequently amplified, and its expression is upregulated in most high-grade serous carcinomas but not in type I tumors." (PMID 22028712, 2012).
viral infections (2 papers, 2018 to 2020). "We confirmed variants with putative driver role of MAP10, MPZL1, RPS6KA1, SETD1B, TAOK2, TMEM127, and TNFRSF1A genes, and of genes linked to viral infections (DDX3X and RSF1) and DNA repair (PAXIP1)." (PMID 32321919, 2020). "During viral infections in humans, SP110 has been shown to interact with the Remodelling and Spacing Factor 1 (RSF1) and Activating Transcription Factor 7 Interacting Protein (ATF7IP), suggesting it is involved in chromatin remodelling." (PMID 30082726, 2018).
bladder cancer (1 paper, 2022). "Our results showed that the expression levels of miR-154-5p and RSF1 were up-regulated in recurrent bladder cancer while RUNX2 was down-regulated, and the differences were insignificant." (PMID 36199571, 2022).
breast tumors (1 paper, 2013). "Fluorescent in-situ hybridization was performed on a tissue microarray of 495 breast tumors (74% of patients) to measure CCND1 and RSF1 copy number." (PMID 24367492, 2013). "Thus, as expected, RSF1 and CCND1 genes were frequently co-amplified in this cohort of breast tumors." (PMID 24367492, 2013).
colon cancer (1 paper, 2021). "Overexpression of RSF1 is associated with poor prognosis in colorectal cancer, and knock-down of RSF1 leads to decrease of cell proliferation, indicating that, in addition to its antiinflammatory effects, mesalazine may act through inhibition of RSF1 in its chemopreventative effects on colon cancer." (PMID 34320178, 2021). "For example, the drug mesalazine, used to treat inflammatory bowel disease but with an apoptosis-inducing and chemopreventative effect in colon cancer; DTI-Voodoo predicts mesalazine to interact with five proteins with PHD-type zinc finger domain: BRPF1, TRIM33, BAZ1A, RSF1 and DPF2." (PMID 34320178, 2021).
endometriosis (1 paper, 2022). The growth of functional endometrial tissue in anatomic sites outside the uterine body. "Most notably, ARID1A in endometriosis-related OC, SMARCA4, and SMARCB1 in hypercalcemic type small cell ovarian carcinoma (SCCOHT), ACTL6A, CHRAC1, RSF1 amplification in high-grade serous OC." (PMID 36430148, 2022).
esophageal cancer (1 paper, 2025). A primary or metastatic malignant neoplasm involving the esophagus. "Our analyses revealed that miR-1224-5p, miR-150-5p, and miR-185-5p were significantly upregulated in esophageal cancer tissues, contrary to a suspected inhibitory role in regulating RSF1 expression." (PMID 40558555, 2025). "Although miR-129-5p was markedly downregulated in esophageal cancer, it exhibited a weak positive correlation with RSF1." (PMID 40558555, 2025). "To assess further the apparent predominance of miR-193b-3p in regulating RSF1 in esophageal cancer, we evaluated the expression levels and correlations of other RSF1-regulating miRNAs previously reported in other tumors." (PMID 40558555, 2025). "However, there have been no studies on miRNA-mediated regulation of RSF1 in esophageal cancer." (PMID 40558555, 2025).
gastric adenocarcinoma (1 paper, 2018). "Increased RSF-1 expression was also reported in other solid tumors including gastric adenocarcinoma and oral cancer." (PMID 29480799, 2018).
gastric cancer (1 paper, 2021). A primary or metastatic malignant neoplasm involving the stomach. "NEAT1 inhibitors and RSF1 inhibitors have opened up new prospects for the treatment of gastric cancer." (PMID 34147108, 2021). "High expression levels of lncRNA nuclear paraspeckle assembly transcript (NEAT1) and RSF1 and low expression levels of miR-1224-5p coexist in gastric cancer." (PMID 34147108, 2021).
hepatocellular carcinoma (1 paper, 2021). A malignant tumor that arises from hepatocytes. "Thus, RSF1 inhibitors can be used to reduce the incidence of HBV-associated hepatocellular carcinoma by preventing RSF1 from recruiting HBX to kinetochores in RSF1-overexpressing LIHC." (PMID 34147108, 2021).
metastatic disease (1 paper, 2025). "Therapeutic strategies aimed at restoring miR-193b-3p expression or inhibiting RSF1 may offer new avenues for targeted treatment, particularly for patients with advanced or metastatic disease." (PMID 40558555, 2025).
myxofibrosarcoma (1 paper, 2023). A malignant fibroblastic neoplasm arising from the soft tissue. "RSF1 gene is amplified in a significant subset of myxofibrosarcomas and resides on 11q13-14.1, where RSF1 and PAK1 are the only two significantly upregulated genes with gained copies in this region." (PMID 37564209, 2023).
pancreatic adenocarcinoma (1 paper, 2021). "We found that RSF1 is overexpressed in CHOL, ESCA, STAD, LGG, THYM, DLBC, and pancreatic adenocarcinoma (PAAD) tumour tissues compared with the corresponding normal tissues." (PMID 34147108, 2021).
cancer (15 papers, 2012 to 2025). A tumor composed of atypical neoplastic, often pleomorphic cells that invade other tissues. "Overexpression of RSF1 is frequently observed in various cancers and is often associated with poor prognosis, enhanced tumor aggressiveness, and therapy resistance." (PMID 40558555, 2025). "Previous studies have shown a correlation between RSF1 upregulation and tumor aggressiveness in multiple cancer types, potentially by causing chromosomal instability." (PMID 28629429, 2017). "Conversely, RSF1 (Remodeling and Spacing Factor 1) gain of function is observed in a variety of human cancers, and is directly associated with tumor aggressiveness, poor therapeutic response, reduced survival, and poor prognosis." (PMID 28704968, 2017). "The analyses revealed a significant upregulation of RSF1 mRNA expression in ESCC cancer tissues compared to adjacent normal tissues." (PMID 40558555, 2025). "Mechanistic studies link RSF1 to cancer progression through various pathways, including enhancing NF-κB-mediated chemoresistance, maintaining genomic stability, and facilitating DNA damage repair." (PMID 40862741, 2025). "This highlights the role of chromatin dynamics in cancer progression and underscores the importance of the miR-193b-3p/RSF1 axis in modulating the epigenetic landscape of ESCC." (PMID 40558555, 2025). "Collectively, the previous and our present studies reinforce the concept that RSF1 is a universal oncogenic driver with cancer-specific nuances." (PMID 40558555, 2025). "RSF1 is frequently overexpressed across diverse human cancers and consistently correlates with aggressive tumor behavior and poor clinical outcomes." (PMID 40862741, 2025). "The RSF-1 complex protein expression correlates with cancer stage and poor clinical outcomes in OC patients." (PMID 36430148, 2022). "Theremodeling and spacing factor-1 (RSF-1) is an oncogene factor thatis high expressed in cancer cells." (PMID 33095554, 2020). "Seventy-three cases, 18 of normal tissues (90.0 %), 22 CINs (55.0 %) and 33 (20.6 %) carcinomas, were found to show undetectable RSF-1 expression." (PMID 29480799, 2018). "Another chromatin remodeler frequently deregulated in cancer is RSF-1, a member of ISWI family found up-regulated in OSCC, which displays increased tumor invasion, lymph node metastasis, and advanced tumor stages." (PMID 28704968, 2017). "Moreover, inhibition of RSF1 has been shown to reduce the proliferation of cancer cells, further supporting the notion that elevated RSF1 levels promote cell survival and tumor growth." (PMID 40558555, 2025). "In gastric cancer, miR-1224-5p is also involved in RSF1 regulation, influencing cancer progression." (PMID 40558555, 2025). "Rsf-1 is a histone chaperone mediating ATP-dependent chromatin remodeling, which is necessary and essential for transcriptional activation (or repression) as well as for cell cycle progression and DNA replication, which are typical of cancer pathogenesis." (PMID 38275417, 2024). "The results of this study suggest that RSF-1 may be involved in enhancing drug resistance in cancer cells by enhancing NFKB signaling." (PMID 35715750, 2022). "CHRAC complexes (CHRAC1, RSF1, POLE3) are known oncogenic drivers regulating proliferation and survival in many cancer types." (PMID 36430148, 2022). "Some preclinical studies using CRISPR/Cas9 technology have highlighted the importance of some genes, including SLFN11, APE1, RSF1, and CDK5, in cancer drug resistance." (PMID 35715750, 2022). "We also found that the enrichment score of RSF1 + Macro-C1, NAP1L1 + Macro-C2, and DEK + Macro-C3 clusters have a positive correlation with Cancer immunity cycles score and immunoregulation-related pathways score which indicated a high activity level of all cancer immunity steps." (PMID 38057779, 2023).
tumor (11 papers, 2012 to 2025). "Collectively, these findings demonstrate that RSF1 is critical for sustaining ESCC tumor growth in vivo, and its loss significantly impairs the tumorigenic potential of high-RSF1-expressing ESCC cells." (PMID 40862741, 2025). "Similarly, in hepatocellular carcinoma, elevated RSF1 levels have been linked to malignant progression through its influence on key cell cycle checkpoints, leading to uncontrolled cell division and tumor growth." (PMID 40558555, 2025). "In this study, we identified miR-193b-3p functioning as a tumor suppressor in ESCC by directly targeting RSF1." (PMID 40558555, 2025). "Collectively, these findings confirmed that miR-193b-3p negatively regulates ESCC progression through RSF1, highlighting the central role of RSF1 in ESCC tumor progression." (PMID 40558555, 2025). "Both datasets revealed significantly elevated RSF1 mRNA levels in ESCC tumor tissues compared to matched adjacent non-tumor tissues." (PMID 40862741, 2025). "This pro-apoptotic phenotype correlated with upregulation of pro-apoptotic BAX, and downregulation of anti-apoptotic BCL-2, indicating RSF1 sustains tumor cell survival by regulating the mitochondrial apoptotic pathway." (PMID 40862741, 2025). "To validate these findings, we employed tissue microarray immunohistochemistry to compare RSF1 protein levels in ESCC tumor tissues with adjacent normal tissues." (PMID 40558555, 2025). "This study, combining public database analysis and clinical sample validation, reveals significantly elevated RSF1 expression in ESCC tumor tissues, confirmed further in an ESCC orthotopic model." (PMID 40862741, 2025). "Bioluminescence imaging (IVIS) showed a markedly slower rate of tumor progression in the RSF1 knockout group compared to controls." (PMID 40862741, 2025). "The results confirmed that RSF1 protein levels were significantly higher in tumor tissues relative to adjacent normal counterparts." (PMID 40558555, 2025). "Reduced Ki-67 expression further confirmed RSF1′s critical role in maintaining the highly proliferative state of tumor cells." (PMID 40862741, 2025). "To assess the effect of AgomiR-193b-3p on RSF1 levels, we extracted proteins from tumor tissues of both experimental and control groups." (PMID 40558555, 2025). "On the other hand, Gepia database revealed that in CC tumor tissues, RSF-1 expression is positively correlated with VEGFA, AKT1 and GSK3β expression." (PMID 36056431, 2022). "The knockdown of linc00958 inhibited RSF-1 and Ki67, curbing tumor growth; it also inhibited VEGFA and CD34, decreasing angiogenesis in mice." (PMID 36056431, 2022). "It is worth noting that SNF2H is also overexpressed in RSF1-overexpressing tumours based on the TCGA and GTEx databases." (PMID 34147108, 2021). "Because BAZ1A, BAZ1B and BAZ2A form other remodelling complexes with SNF2H, RSF1 recruits SNF2H from other remodelling complexes to the RSF remodelling complex in RSF1-overexpressing tumours." (PMID 34147108, 2021). "SNF2H downregulation or disruption of the interaction between SNF2H and RSF1 enhances paclitaxel sensitivity in tumour cells with RSF1 overexpression." (PMID 34147108, 2021). "RSF1 is overexpressed in various tumor tissues based on recent studies and the TCGA database, including breast cancer, HCC, Glioma, etc.." (PMID 34736517, 2021). "Previous studies on a variety of tumor types have shown the correlation between RSF-1 overexpression and poor clinical outcomes in cancer patients." (PMID 29480799, 2018). "Multiple studies have demonstrated the tumor-promoting interplays between RSF-1 and known oncogenes or tumor suppressors, such as cyclin D1, cyclin E1, retinoblastoma (RB) and breast cancer susceptibility gene 1 (BRCA1)." (PMID 29480799, 2018). "The in vivo experiment revealed that RSF1 knockout significantly inhibited tumor growth over time." (PMID 40862741, 2025). "Furthermore, our immunodeficient mouse model precludes assessment of RSF1′s impact on the tumor immune microenvironment." (PMID 40862741, 2025).
tumor (continued). "In bladder cancer, miR-154 reduces RSF1 expression, thereby inhibiting tumor growth and metastasis." (PMID 40558555, 2025). "Furthermore, transfecting miR-193b-3p mimics into ESCC cell lines to elevate its level led to a significant reduction in RSF1 level and in cell proliferation, migration, and invasion, corroborating its role as a tumor suppressor." (PMID 40558555, 2025). "In xenograft models using immunodeficient mice, RSF1 depletion markedly inhibited tumor growth." (PMID 40862741, 2025). "In particular, RSF-1 overexpression (scores of 9+ to 12+).correlates with bigger tumor size (p = 0.0015), poor differentiation (p = 0.0097), nodal metastasis (p = 0.0001), and tumor stages (p < 0.0001)." (PMID 29480799, 2018). "Collectively, these results indicate that RSF1 is required for ESCC cell proliferation, migration, and invasion, underscoring its critical role in ESCC tumor progression." (PMID 40862741, 2025). "Genetic ablation of RSF1 potently suppressed ESCC cell proliferation, migration, invasion, and tumor growth in vivo, while reconstitution of RSF1 rescued these oncogenic phenotypes." (PMID 40862741, 2025). "In this study, we successfully knocked out the RSF1 gene using CRISPR/Cas9 technology in ESCC cell lines (KYSE450 and EC9706) and demonstrated its tumor-promoting function through both in vitro and in vivo experiments." (PMID 40862741, 2025). "Functional assays show that RSF1 knockout (KO) significantly inhibits ESCC cell proliferation, migration, invasion, and in vivo tumor growth, while reintroducing RSF1 restores its oncogenic effects." (PMID 40862741, 2025). "In this research, we further discovered that in vitro, depletion of RSF-1 in SiHa/DDP cells could attenuate the cisplatin resistance and tube formation; in xenograft mice, RSF-1 was decreased by the knockdown of linc00958 and associated with the inhibition of tumor growth and angiogenesis." (PMID 36056431, 2022). "Compared with that in normal tissues and cells, small nucleolar RNA host gene 6 (SNHG6) and RSF1 expression are upregulated, while miR-490-3p expression is downregulated, in NSCLC tumours and cell lines." (PMID 34147108, 2021). "Taken together, this study reported a new regulatory axis linc00958/miR-185-5p/RSF-1 in cisplatin resistance and tube formation in CC via AKT1/GSK3β/VEGFA pathway and knockdown of linc00958 could also inhibit the tumor growth and angiogenesis." (PMID 36056431, 2022). "Hence, in this study, we investigated the regulatory effect of linc00958/miR-185-5p/RSF-1 on cisplatin resistance in SiHa/DDP cells and tube formation in vitro; in xenograft mice, we further validated the role of linc00958 in tumor growth and angiogenesis." (PMID 36056431, 2022). "Although a pull-down assay confirmed that cyclin E1 binds with the first 441 amino acids of RSF1, full-length RSF1, but not the minimal binding domain of RSF1, has a tumour-promoting function." (PMID 34147108, 2021). "We found that RSF1 was overexpressed in cholangiocarcinoma (CHOL), head and neck squamous cell carcinoma (HNSC), liver hepatocellular carcinoma (LIHC) and stomach adenocarcinoma (STAD) tumour tissues compared with adjacent normal tissues." (PMID 34147108, 2021). "IHC showed that RSF-1 and the tumor growth biomarker Ki67, were inhibited in the group where linc00958 was knocked down, revealing that linc00958 downregulation in mice could inhibit RSF-1 and Ki67, suppressing the tumor growth." (PMID 36056431, 2022).
infection (2 papers, 2009 to 2020). The state of being infected such as from the introduction of a foreign agent such as serum, vaccine, antigenic substance or organism. "Yet, it cannot be excluded that host RNAPs transcribe some genes of AR9, RSL2, and RSF1 required for efficient infection." (PMID 32977622, 2020). "The effect of rifampicin on infection was also investigated for four jumbo phages infecting Ralstonia solanacearum-phiRP12, phiRP31, RSL2, and RSF1." (PMID 32977622, 2020). "Endogenous mRNA levels of the chromatin remodelling and spacing factor 1 gene (RSF1) were significantly different between PBMC from N'Dama and Boran before infection (2.6-fold higher in Boran, P = 0.0109)." (PMID 19409086, 2009).
RSF1 also shares sentences with these, for which no sentence is quoted: ovarian clear cell cancer (2 papers); Ataxia (1); atherosclerosis (1); colorectal cancer (1); inflammatory bowel disease (1); kidney clear cell carcinoma (1); metastatic cancer (1); neurodevelopmental disorder (1); oral cancer (1); pancreatic neuroendocrine tumor (1); prostate carcinoma (1); skin melanoma (1).